IL10 (interleukin 10)
Diseases named in the same sentence as IL10 in open-access papers (continued):
Sharing a sentence is not in itself a finding about the gene and the disease.
cavernoma (1 paper, 2015). "At 6 months, Il10 expression persisted in the PCS group, where portal inflow is patent via the cavernoma, demonstrated on CT imaging." (PMID 26020934, 2015).
central nervous system infection (1 paper, 2021). "During persistent central nervous system infection sustained by coronaviruses neurotropic strains, IL-10 mRNA is upregulated, and IL-10 deficiency is associated to broader virus-induced CNS damage." (PMID 34696451, 2021).
cerebral (1 paper, 2023). "EA and iPSC-EVs treatments significantly improved neurological function and neuronal and intestinal tract injury, downregulated the levels of IL-17 expression and upregulated IL-10 levels in brain and colon tissue after cerebral ischemia−reperfusion." (PMID 36742316, 2023).
cerebral artery occlusion (1 paper, 2013). "Administration of exogenous IL-10 centrally and systemically decreases the infarct size in rats after permanent focal ischemia, while IL-10 knockout mice showed larger infarct volume following middle cerebral artery occlusion." (PMID 24499655, 2013).
cerebral atherosclerosis (1 paper, 2022). Atherosclerosis of the cerebral vasculature. "IL-10 is a very potent trigger of M2c and thus inhibited in the interfering experiment, resulting in suppression of features of cerebral atherosclerosis." (PMID 35935990, 2022).
cerebrovascular disease (1 paper, 2024). "Clinical applications include improvement of microcirculation in the epicardium and coronary arteries and attenuation of inflammatory responses through secretion of IL-10 and inhibition of NF-κB, as well as improving neurological function and angiogenesis in cerebrovascular disease." (PMID 39859963, 2024).
Chédiak–Higashi syndrome (1 paper, 2019). "Additionally, gingival atypical fibroblasts in cases of Chédiak–Higashi syndrome significantly intensify the expression of IL-4 and IL-10 along with other cytokines." (PMID 31443525, 2019).
Chronic diarrhea (1 paper, 2022). The presence of chronic diarrhea, which is usually taken to mean diarrhea that has persisted for over 4 weeks. "Our data also suggested that FMT intervention obviously increased the level of IL-10 and decreased the levels of IL-6, IL-8, IL-1β, and IFN-γ in chronic diarrhea monkey serum during the intervention, especially on Day-8." (PMID 36551772, 2022).
Chronic fatigue (1 paper, 2023). Subjective feeling of tiredness characterized by a lack of energy and motivation that persists for six months or longer. "In vivo, JP could increase the levels of IL-2, IL-4, and IL-10 in the serum of mice treated with cyclophosphamide, increase the level of IL-2 in the serum of chronic fatigue (CFS) rats, and decrease the level of IL-10." (PMID 37959774, 2023).
chronic kidney failure (1 paper, 2023). "IL-10 participates in the regulation and maintenance of normal kidney function, but an abnormal expression contributes to acute and chronic kidney failure." (PMID 37425258, 2023).
chronic myelomonocytic leukemia (1 paper, 2016). A myelodysplastic/myeloproliferative neoplasm which is characterized by persistent monocytosis, absence of a Philadelphia chromosome and BCR/ABL fusion gene, fewer than 20 percent blasts in the bone marrow and blood, myelodysplasia, and absence of PDGFRA or PDGFRB rearrangement. "In vitro, IL-10 has been found to inhibit cell growth and granulocyte/macrophage colony stimulating factor production in chronic myelomonocytic leukemia cells, as well as inhibiting cytokine production and growth in JMML cells." (PMID 26822028, 2016).
chronic thromboembolic pulmonary hypertension (1 paper, 2024). Chronic thromboembolic pulmonary hypertension (CTEPH) is characterized by the persistence of thromboemboli in the form of organized tissue obstructing the pulmonary arteries. "Also, in patients with chronic thromboembolic pulmonary hypertension (CTEPH), different cytokines showed increased levels, such as IL-1β, IL-2, IL-4, IL-6, IL-8 and IL-10." (PMID 38612795, 2024).
chronic widespread pain (1 paper, 2019). Chronic pain that is felt all over the body. "Comparable results indicating lowered levels of anti-inflammatory cytokines were reported in a study that examined IL-4 and IL-10 gene expression patterns and serum concentrations in chronic widespread pain patients including FM." (PMID 31470635, 2019).
Classical Hodgkin lymphoma (1 paper, 2025). "Classical Hodgkin lymphoma secretes IL-10, TGF-β, and chemokines that attract regulatory T cells and suppress cytotoxic immunity, while also overexpressing PD-L1 factors linked to immune evasion and adverse outcomes." (PMID 40801653, 2025).
cleft palate (1 paper, 2023). Cleft palate is a fissure type embryopathy that affects the soft and hard palate to varying degrees. "The correlations between the studied factors (HBD-2, HBD-3, HBD-4, LL-37, and IL-10) proved the synergistic involvement of common local defense factors in postnatal cleft palate morphopathogenesis." (PMID 37508659, 2023).
clostridium difficile infection (1 paper, 2019). Symptomatic infection due to the spore-forming bacterium clostridium difficile. "During the entire time period from 1998 through 2018, dysbiosis had the highest burst strength, followed by Clostridium difficile infection, 16s rRNA, Interleukin 10 deficient mice, and fecal microbiota transplantation." (PMID 30819194, 2019).
CNS demyelinating diseases (1 paper, 2024). "Alternatively, the polysaccharide A of Bacteroides fragilis can directly induce differentiation of naïve CD4+ T cells to IL-10 producing FoxP3 + Treg cells, thereby conferring protection against CNS demyelinating diseases." (PMID 38352704, 2024).
CO poisoning (1 paper, 2025). "In summary, this MR study provides genetic evidence supporting a potential causal role of IL-10, IL-1β, and IL-13 in the pathogenesis of CO poisoning." (PMID 40988268, 2025). "In the context of CO poisoning, where a prompt and effective inflammatory response might be crucial for limiting initial damage, overexpression of IL-10 and IL-13 may paradoxically inhibit protective responses." (PMID 40988268, 2025).
cocaine addiction (1 paper, 2015). "The plasma concentrations of interleukin 1-beta (IL-1β), IL-6, IL-10, and tumor necrosis factor-alpha (TNFα) were affected by history of cocaine addiction and sex." (PMID 25762940, 2015). "In relation to IL-10, history of cocaine addiction (F1,122 = 8.69, p = 0.004) and sex (F1,122 = 11.14, p = 0.001) had a significant primary effect on the IL-10 concentrations." (PMID 25762940, 2015).
complement deficiency (1 paper, 2021). A genetic deficiency of any of the component of the complement system (including the classical, alternative, and terminal pathway components), that can either be acquired or inherited. "Ex vivo intestinal IL-10 production was also elevated in females after Sham treatment with no increased in response to IR in wildtype or complement deficiency." (PMID 33868287, 2021).
constrictive pericarditis (1 paper, 2013). A heart disorder in which the pericardial sac becomes thickened and fibrotic, tightening the myocardium and impeding the normal myocardial function. "Patients with ECP had higher median levels of IL-10 (38.5 versus 0.2 pg/ml, P<0.001) and TGF-β (121.5 versus 29.1 pg/ml, P=0.02) in the serum compared to those with effusive non-constrictive pericarditis." (PMID 24155965, 2013).
corneal ulcer (1 paper, 2022). Area of epithelial tissue loss from corneal surface; associated with inflammatory cells in the cornea and anterior chamber. "The IL10 SNP rs6703630 allele A, which had been associated with a low IL-10 production, was more common in patients with corneal ulcers than in controls." (PMID 36422638, 2022).
coronary artery aneurysm (1 paper, 2019). "Inconsistent reports exist on the association of IL-10 polymorphisms with KD susceptibility and Coronary Artery Aneurysms (CAA)." (PMID 31908741, 2019).
cranial nerve palsies (1 paper, 2025). "In the CARTITUDE-4 trial, patients who developed cranial nerve palsies were likewise found to have elevated levels of interleukins, specifically IL-10 and IL-2Ra, as well as greater CAR T-cell expansion compared to patients without neurologic involvement." (PMID 41323217, 2025).
Creutzfeldt-Jakob disease (1 paper, 2021). "Both IL-10 and IL-4 were detected in CSF of patients with Creutzfeldt-Jakob disease (CJD)." (PMID 34394070, 2021).
cystic tumors (1 paper, 2024). "Cystic tumors exhibited higher expression of IL1B, IL6, IL10, and TNF (all P < 0.05) than non-cystic tumors." (PMID 38965454, 2024).
cystinosis (1 paper, 2019). Cystinosis is a metabolic disease characterized by an accumulation of cystine inside the lysosomes, causing damage in different organs and tissues, particularly in the kidneys and eyes. "Here, we explored if macrophage polarization to either proinflammatory M1-like M(LPS/IFNγ) or anti-inflammatory M2-like M(IL-4/IL-10) affected TNT-like protrusion formation, intercellular transport and, ultimately, the efficacy of cystinosis prevention." (PMID 31601865, 2019).
dacryoadenitis (1 paper, 2016). Inflammation and enlargement of the lacrimal gland. "Furthermore, the expression of IL-10, a signature cytokine for Tregs that suppresses Th1/Th17 responses, was dramatically upregulated in the LGs of dacryoadenitis rabbits treated with ADSCs." (PMID 27699412, 2016).
Delusion (1 paper, 2022). A delusion is a fixed false belief held despite evidence to the contrary. "IL-10 is positively correlated with the ToM in chronic patients with delusions but not in nondelusional patients or healthy controls." (PMID 35887634, 2022).
dermatophytosis (1 paper, 2019). A common fungal infection of the stratum corneum of the skin, hair, or nails by a dermatophyte. "This regulation would not take place in monocytes from recurrent dermatophytosis patients, which secrete significantly more IL-10 than normal controls or tinea pedis patients." (PMID 31824444, 2019).
diabetic cardiomyopathy (1 paper, 2024). Diabetic cardiomyopathy is a disorder of the heart muscle in people with diabetes. "They proposed that a chronic training intervention is an effective preventive and curative approach to ameliorate diabetic cardiomyopathy by modulating the NLRP3 inflammasome and subsequently reducing inflammation, a finding confirmed by our results (i.e., decreased IL1β and increased IL10 levels)." (PMID 38532054, 2024).
diarrheal disease (1 paper, 2012). The condition of having at least three loose or liquid bowel movements each day. "Since the mice developed a pasty stool which is a sign of murine diarrheal disease, we measured the expression of NHE3, the dominant salt-absorptive transporter in the proximal part of the colon in IL-10−/− mice." (PMID 22848392, 2012).
dilated cardiomyopathy (1 paper, 2015). Cardiomyopathy which is characterized by dilation and contractile dysfunction of the left and right ventricles. "It was demonstrated that circulating levels of IL-10 increased in relation to elevated TNF-α levels in patients with dilated cardiomyopathy and may support the concept that the increase of IL-10 levels enhances the release of sTNFR2." (PMID 26539513, 2015).
ductal carcinoma (1 paper, 2022). "The expression level of B7-H4 is higher in M2-type macrophages than in M1-type macrophages in infiltrating ductal carcinoma tissues, and the secretion of IL-10 is positively correlated with the expression of B7-H4." (PMID 36514159, 2022).
dyskeratosis congenita (1 paper, 2022). Dyskeratosis congenita (DC) is a rare ectodermal dysplasia that often presents with the classic triad of nail dysplasia, skin pigmentary changes, and oral leukoplakia associated with a high risk of bone marrow failure (BMF) and cancer. "IL-10 pathway deficiency, XLP-2 CGD, Dyskeratosis congenita." (PMID 35757131, 2022). "Notably, the possibility to present with IBD as a first sign (potentially in the first year of life) is proper of defects of the IL-10 molecular pathway and defects influencing the gut epithelial barrier, such as the dyskeratosis congenita." (PMID 35757131, 2022).
energy metabolism disorder (1 paper, 2016). "Except for IL-10, all these biomarkers of LIRI and its related energy metabolism disorder were significantly inhibited by RvD1 treatment." (PMID 27009328, 2016).
enthesitis related arthritis (1 paper, 2013). "Furthermore, we observed higher concentrations of the anti-inflammatory cytokine IL-10 in patients with oligoarthritis, seronegative polyarthritis and enthesitis related arthritis compared to healthy subjects (unpublished data)." (PMID 23497095, 2013).
eosinophilic diseases (1 paper, 2012). "Indeed, eosinophilic diseases have been associated with TNFα, IL-5, IL-10, and eotaxin-3, while IL-10 was overexpressed in IgG4RD." (PMID 22333532, 2012).
epididymitis (1 paper, 2022). Inflammation of the epididymis. "Moreover, the expression level of IL-6 and IL-10 was upregulated 30-fold and 5-fold in CE compared with the controls, which was also proved to be the epididymitis characteristics through mouse model induced by Gram-negative (LPS) and Gram-positvie (LTA) stimulation." (PMID 35634321, 2022).
Epileptic spasm (1 paper, 2024). A sudden flexion, extension, or mixed extension-flexion of predominantly proximal and truncal muscles that is usually more sustained than a myoclonic movement but not as sustained as a tonic seizure. "Although IL-10 might be related to the cessation of epileptic spasms, we did not perform immunological investigations in the present case." (PMID 38903324, 2024).
epistaxis (1 paper, 2022). Bleeding from the nose. "As evidenced by the results of the present study, IL-17A is the main cytokine which participates in the pathogenesis of idiopathic epistaxis; moreover, in association with IL-10, it can be regarded as the suppressor of IFN- in patients." (PMID 35145935, 2022). "As evidenced by the results of the present study, IL-17A is the main cytokine that participates in the pathogenesis of idiopathic epistaxis; moreover, in association with IL-10, it can be regarded as the suppressor of IFN- in patients with epistaxis." (PMID 35145935, 2022). "Data analysis in the male and female patients with epistaxis, in comparison with male and female controls, also confirmed the results and revealed that the serum levels of IL-17A and IL-10, as well as IFN-, had the same patterns in all patients." (PMID 35145935, 2022). "In the present study, IL-17A, IL-23, IFN-γ, IL-4, and IL-10 serum levels were compared between patients with idiopathic epistaxis and normal controls." (PMID 35145935, 2022). "The serum levels of IL-4, IL-10, IL-17A, IL-23, and IFN- were evaluated in 90 patients with idiopathic epistaxis and 90 healthy controls using enzyme-linked immunosorbent assay (ELISA) technique." (PMID 35145935, 2022). "The results also indicated that IL-10 serum levels were higher in patients with epistaxis, as compared to those in healthy controls." (PMID 35145935, 2022). "The results pointed out that IL-17A and IL-10 serum levels were increased in patients with idiopathic epistaxis, as compared to those in the controls." (PMID 35145935, 2022). "Due to the increased production of IL-10 in patients with epistaxis, it may be concluded that the up-regulation of IL-10 is a normal immune response to increased expression of IL-17A, performing regulatory functions to modulate tissue damage roles of IL-17A." (PMID 35145935, 2022). "Therefore, the IFN-, IL-4, and IL-10 serum levels were also determined in patients with epistaxis in comparison with healthy controls." (PMID 35145935, 2022). "Moreover, IL-10 serum levels significantly increased (P<0.001) in patients with epistaxis (100.67±3.56 pg/mL), compared to those obtained in healthy controls (68.33 ± 2.24 pg/mL)." (PMID 35145935, 2022). "Furthermore, female patients with epistaxis had higher IL-10 serum levels." (PMID 35145935, 2022). "The statistical analysis showed that IL-17A and IL-10 serum levels significantly increased and IFN- decreased in both male and female patients with epistaxis, as compared to those in male and female healthy controls, respectively (P<0.001 for all)." (PMID 35145935, 2022). "Nonetheless, IL-17A (P=0.325), IL-23 (P=0.930), IFN- (P=0.860), IL-4 (P=0.313), and IL-10 (P=0.158) serum levels did not change in epistaxis patients with and without a familial history of epistaxis." (PMID 35145935, 2022). "Furthermore, IL-17A (P= 0.760), IL-23 (P=0.658), IFN- (P=0.961), IL-4 (P=0.370), and IL-10 (P=0.487) serum levels did not change in female and male patients with epistaxis." (PMID 35145935, 2022).
equine disease (1 paper, 2019). "The future experiments may be designed to determine the immune modulating activity of recombinant horse IL-4 and IL-10 in equine disease model." (PMID 31190704, 2019).
Esophageal stricture (1 paper, 2021). A pathological narrowing of the esophagus that is caused by the development of a ring of scar tissue that constricts the esophageal lumen. "Therefore, it was difficult to conclude that there is no benefit of steroid for prevent esophageal stricture owing to no significance difference in IL-10 between two groups of caustic patients." (PMID 34793546, 2021).
eumycetoma (1 paper, 2013). "Moreover, IL-10 levels were significantly elevated in serum of M. mycetomatis eumycetoma patients in Sudan, suggesting that IL-10 concentrations also play an important role in development or maintenance of eumycetoma." (PMID 23717704, 2013).
Exotropia (1 paper, 2021). A form of strabismus with one or both eyes deviated outward. "The levels of IL-6, IL-10, IL-17A, IL-12P70, INF-γ, and TNF-α were detected in tears in patients with concomitant exotropia and healthy controls matched by age and gender through the Simoa technology." (PMID 34659636, 2021).
Fabry disease (1 paper, 2022). Fabry disease (FD) is a progressive, inherited, multisystemic lysosomal storage disease characterized by specific neurological, cutaneous, renal, cardiovascular, cochleo-vestibular and cerebrovascular manifestations. "The rSNPs proposed here could modulate the clinical phenotype of Fabry disease, so we propose that IL10, TGFB1 and EDN1 genes be considered modifier/minor genes in FD, in charge of regulating its neuro-cardiovascular variant." (PMID 36138766, 2022).
Farber disease (1 paper, 2023). "Additionally, increased plasma levels of IL6, IL10, IL12, CCL2, CCL3, CXCL1, and VEGF and substantial central nervous system defects have been observed in patients with Farber disease." (PMID 37189685, 2023).
fish disease (1 paper, 2025). Diseases of freshwater, marine, hatchery or aquarium fish. "In fish, IL-10 may also be correlated with anti-inflammatory properties and may play a significant role in fish disease." (PMID 41012187, 2025).
Focal cortical dysplasia (1 paper, 2024). A type of malformation of cortical development that primarily affects areas of neocortex. "Furthermore, aberrant expression of cytokines and chemokines together with their receptors, such as downregulation of IL-10, has been reported in individuals with hippocampal sclerosis and focal cortical dysplasia." (PMID 38605125, 2024).
focal epilepsy (1 paper, 2024). A seizure caused by a localized disorder. "IL-10 proved essential in reinforcing GABAergic currents while inhibiting IL-10 signaling, thereby contributing to the suppression of focal epilepsy." (PMID 39259090, 2024). "In our MR study, patients diagnosed with focal epilepsy exhibited heightened levels of IL-10, a vital anti-inflammatory cytokine." (PMID 39259090, 2024). "Specifically, focal epilepsy onset may induce increases in cytokines such as IL-7, IL-1Ra, IL-10, TNF-α, IFN-γ, and IL-1β, whereas inconsistent cytokine levels, including IL-5 and IL-1ra, may influence variations in focal epilepsy risk." (PMID 39259090, 2024).